MITA1 (metabolism induced tumor activator 1)
Synonyms: IL7AS; hNAIL
Gene: Long non-coding RNA gene on chromosome 8 (78,805,179 to 78,956,082, forward strand). Ensembl gene ENSG00000285744.
Diseases named in the same sentence as MITA1 in open-access papers:
MITA1 is named in the same sentence as 3 diseases in open-access papers, as found by Europe PMC text mining. Sharing a sentence is not in itself a finding about the gene and the disease. The quoted sentences say what the papers report.
hepatocellular carcinoma (3 papers, 2020 to 2026). A malignant tumor that arises from hepatocytes. "MITA1 (metabolism-induced tumor activator 1) was named from studies in hepatocytes showing that its up-regulation is driven by energy stress and linked to hepatocellular carcinoma metastasis." (PMID 41601641, 2026). "MITA-1 significantly promotes the metastasis of hepatocellular carcinoma by facilitating epithelial – mesenchymal transition (EMT), which is an early and essential process in cancer metastasis." (PMID 39697114, 2025). "Additionally, MITA-1 expression was found to be up-regulated in hepatocellular carcinoma." (PMID 39697114, 2025). "Consequently, MITA-1 May promote EMT by upregulating Slug transcription, suggesting that the AMPK/MITA-1/EMT pathway could serve as a potential therapeutic target for hepatocellular carcinoma." (PMID 39697114, 2025). "The metabolism-induced tumor activator 1 (MITA1) is an lncRNA which has been shown to be over-expressed in hepatocellular carcinoma (HCC) and participates in the metastatic potential of these cells." (PMID 33123468, 2020).
liver cancer (1 paper, 2025). An epithelial or non-epithelial malignant neoplasm that arises from the liver. "The reduction of MITA-1 resulted in decreased Slug expression, whereas the overexpression of Slug significantly mitigated the impact of MITA-1 deletion on the migration and invasion of liver cancer cells." (PMID 39697114, 2025).
MITA1 also shares sentences with these, for which no sentence is quoted: lung carcinoma (1 paper).